ANKRD30B (ankyrin repeat domain 30B)
Synonyms: NY-BR-1.1
Tractability: No criterion of Open Targets' tractability assessment is met for any kind of drug.
Gene: Protein-coding gene on chromosome 18 (14,728,272 to 14,854,667, forward strand). Ensembl gene ENSG00000180777.
Subcellular location (Human Protein Atlas): Nucleoli; Nucleoplasm
Genetic constraint (gnomAD): Loss-of-function variants: 84 observed, 102.67 expected, observed/expected ratio (o/e) 0.82, 90% interval 0.69 to 0.98. The upper end of that interval is the gene's LOEUF score, 0.98, which puts it in group 4 of 6, group 1 being the genes least tolerant of losing a copy. Missense variants: 1,076 observed, 1,069.8 expected, observed/expected ratio (o/e) 1.01, 90% interval 0.96 to 1.06. Synonymous variants: 371 observed, 368.35 expected, observed/expected ratio (o/e) 1.01, 90% interval 0.92 to 1.1.
Homologues: Orthologues: tropical clawed frog ankrd7 (14% identical), zebrafish si:ch211-272n13.3 (6% identical), Caenorhabditis elegans lem-3 (6% identical), Drosophila melanogaster CG8679 (5% identical), Caenorhabditis elegans F44E5.15 (2% identical), Drosophila melanogaster CG42391 (1% identical), Caenorhabditis elegans K07D4.2 (1% identical). Paralogues in human: ANKRD30A (64% identical), ANKRD26 (30% identical), ANKRD62 (21% identical), ANKRD20A1 (19% identical), ANKRD18B (16% identical), ANKRD18A (16% identical), ANKRD30BL (12% identical).
Diseases named in the same sentence as ANKRD30B in open-access papers:
ANKRD30B is named in the same sentence as 2 diseases in open-access papers, as found by Europe PMC text mining. Sharing a sentence is not in itself a finding about the gene and the disease. The quoted sentences say what the papers report.
cancer (1 paper, 2023). A tumor composed of atypical neoplastic, often pleomorphic cells that invade other tissues. "Very little is known about any association between ankyrin repeat domain 30B (ANKRD30B) and any type of cancer." (PMID 37407629, 2023).
ANKRD30B also shares sentences with these, for which no sentence is quoted: Williams syndrome (1 paper).